STAT5A (signal transducer and activator of transcription 5A)
Diseases named in the same sentence as STAT5A in open-access papers (continued):
Sharing a sentence is not in itself a finding about the gene and the disease.
colon carcinoma (7 papers, 2015 to 2024). "Here, phospho-STAT5 expression is associated with higher levels of cyclin D1 and poor prognosis, and single nucleotide polymorphisms in both STAT5a and STAT5b are linked with colon cancer." (PMID 26938566, 2016). "Together, these results show that the lncRNA TLX1NB promotes colon cancer cell migratory, invasive, and metastatic activity, at least in part by inducing robust STAT5A phosphorylation." (PMID 35502613, 2022). "In conclusion, TLX1NB enhances STAT5A phosphorylation to promote colon cancer cell invasion, migration, and metastasis." (PMID 35502613, 2022). "To further investigate the mechanisms governing TLX1NB-mediated regulation of colon cancer cell invasion and metastasis, we detected the expression levels of STAT5A and p-STAT5A following TLX1NB knockdown or overexpression." (PMID 35502613, 2022). "Case-control studies, using more than 1550 patients with colon cancer and 750 cases of rectal cancer, demonstrated that JAK2, SOCS2, STAT1, STAT3, STAT5A, STAT5B, and STAT6 were associated with colon cancer, and that STAT3, STAT4, STAT6, and TYK2 were linked to rectal cancer." (PMID 36982677, 2023). "Based on the results of previous studies, we hypothesized that TLX1NB promoted colon cancer invasion and metastasis by enhancing STAT5A phosphorylation." (PMID 35502613, 2022). "In addition, we found that TLX1NB promoted the invasion and metastasis of colon cancer cells by enhancing STAT5A phosphorylation." (PMID 35502613, 2022). "Thus, TLX1NB may drive colon cancer cell migration and invasion, at least in part by promoting STAT5A phosphorylation." (PMID 35502613, 2022). "The transcriptome profiling study showed that unphosphorylated STAT5A could repress several genes (e.g., TGFB1 and FOXQ1) involved in colon cancer development." (PMID 39136000, 2024). "We did not compare TLX1NB expression levels in clinical colon cancer samples using qPCR, nor did we clarify the mechanism by which this lncRNA promotes STAT5A phosphorylation." (PMID 35502613, 2022). "Non-phosphorylated STAT5A has also been reported to suppress human and murine colon cancer cell growth in vivo, which is consistent with our data." (PMID 35502613, 2022). "In this study, we investigated the role of TLX1NB in colon cancer invasion and metastasis through a series of wet and dry experiments and reported that TLX1NB enhanced STAT5A phosphorylation to promote colon cancer cell invasion, migration, and metastasis for the first time." (PMID 35502613, 2022). "In rescue assays in which HCT116 cells were treated with pimozide, inhibition of STAT5A phosphorylation reversed the enhanced migration and invasion of colon cancer cells following TLX1NB overexpression, suggesting that pimozide has clinical value for treating colon cancer." (PMID 35502613, 2022).
lymphoma (7 papers, 2012 to 2025). A malignant (clonal) proliferation of B- lymphocytes or T- lymphocytes which involves the lymph nodes, bone marrow and/or extranodal sites. "While previous studies used artificial target sequences, we developed an assay using target DNA sequences from common MLV integration sites in Stat5a and c-myc in the genome of murine lymphomas and successfully integrated MLV into the target DNA in vitro." (PMID 22348097, 2012). "In these lymphomas, expression of Stat5a was commonly upregulated." (PMID 22348097, 2012). "For example, STAT1 and STAT5A genes are silenced by DNA methylation in squamous cell carcinoma of the head and neck (SCCHN) and NPM1-ALK–expressing lymphomas, respectively." (PMID 31530290, 2019). "In summary, STAT3 and STAT5B, but not STAT5A, are relevant therapeutic targets in the treatment of lymphomas." (PMID 31963765, 2020). "The mechanism of lower STAT5A gene expression in NSCLC is not known, however in lymphomas STAT5A was found to be epigenetically silenced." (PMID 25137041, 2014).
anemia (6 papers, 2013 to 2023). A reduction in the number of red blood cells, the amount of hemoglobin, and/or the volume of packed red blood cells. "Furthermore, just one-allele of either Stat5a or Stat5b is sufficient to prevent the perinatal lethality and anemia seen in STAT5-null mice, suggesting that molecular redundancy protects the most critical ‘life-and-death’ functions." (PMID 26999798, 2016). "Hematopoietic deletion of STAT5A/B resulted in anemia, defining STAT5A/B as regulator of iron uptake (control of TFR1 expression) and survival genes in erythroid cells." (PMID 31690038, 2019). "Conversely, Stat5a−/− Stat5b−/− mice exhibited severe microcytic anemia." (PMID 37892192, 2023). "As the prenatal lethality of Stat5a/b−/− mice was connected to severe combined immunodeficiency, erythroid defects, and subsequent anemia, it was somehow surprising that hematopoietic-specific STAT5A/B deletion led to anemia and lymphopenia, but did not influence survival." (PMID 31690038, 2019). "Interestingly, global Stat5a/b−/− mice have a more severe microcytic hypochromic anemia than hematopoietic-specific Stat5a/b−/− mice, suggesting that the role of Stat5 in other cell types may contribute to the severity of the microcytic hypochromic anemia." (PMID 24376517, 2013). "Global Stat5a/b−/− and hematopoietic-specific Stat5a/b−/− mice have a severe microcytic hypochromic anemia that is proposed to be related to the lack of Stat5 binding to the promoter of Irp2 and Tfr1, leading to the inhibition of iron uptake in erythroid cells." (PMID 24376517, 2013).
acute lymphoblastic leukemia (5 papers, 2020 to 2024). Leukemia with an acute onset, characterized by the presence of lymphoblasts in the bone marrow and the peripheral blood. "For example, STAT5A, STAT5B, and STAT5A/B deletion mutations were generated in a T lymphoblastoid cell line using the CRISPR-Cas9 system to investigate the role of STAT5 in glucocorticoid (GC) resistant T cell-acute lymphoblastic leukemia." (PMID 36232600, 2022).
breast tumors (5 papers, 2010 to 2025). "The overexpression of STAT5A in T47D-derived breast tumors results in a reduced tumor size due to increased apoptosis." (PMID 40003884, 2025). "IHC was applied to assess the level of STAT5a in breast tumor specimens collected from patients before neoadjuvant treatment." (PMID 34336684, 2021). "Collectively, these experimental data indicate distinct roles of Stat5a and Stat5b in breast tumor biology." (PMID 23036105, 2012). "We analyzed publicly available (TCGA) RNA-seq datasets and found that patients with high STAT5A mRNA expressing breast tumors had a significantly higher overall survival (p = 0.002) and progression-free interval (p = 0.047) compared to patients with tumors that have low STAT5A." (PMID 34078871, 2021). "However, several putative SRC substrates, including HIPK3, STAT5A, p120, FRK and Hrs, were frequently phosphorylated in multiple breast tumors." (PMID 21049007, 2010). "Analysis of the overlap between substrates phosphorylated in our study and in human tumors defined a group of proteins that may be most relevant to Src activity in human cancers: HIPK3, STAT5A, p120, Hrs and FRK in human breast tumors, and p130Cas, p120, FRK, Hrs and KIAA0323 in human lung tumors." (PMID 21049007, 2010).
colorectal cancer (5 papers, 2014 to 2023). A primary or metastatic malignant neoplasm that affects the colon or rectum. "The association of high STAT5a expression to overall survival appeared unclear in brain, lung, and colorectal cancer." (PMID 37369132, 2023). "An insertion in the DNA binding domain of STAT5A, the Q368Pfs*9 mutation, has been associated with colorectal cancer (Cosmic database COSV61805871)." (PMID 36232600, 2022). "In addition, a study has found that unphosphorylated STAT5a exhibits a tumor suppressor function through binding with heterochromatin protein 1α (HP1α), leading to the stabilization of heterochromatin in colorectal cancer cells." (PMID 37369132, 2023). "Moreover, miR-221 suppresses colorectal cancer metastasis and invasion by down-regulating c-kit Stat5A and ETS1." (PMID 24721839, 2014).
esophageal cancer (5 papers, 2017 to 2023). A primary or metastatic malignant neoplasm involving the esophagus. "CALR promotes migration and invasion of esophageal cancer cells by up-regulating neuropilin-1 expression via STAT5A and neuropilin-1 is a critical downstream effector of CALR in promoting cell migration and invasion." (PMID 29228584, 2017). "CALR also upregulated neuropilin-1 expression via STAT5A in esophageal cancer cells." (PMID 35641480, 2022).
acute myeloid leukemia (4 papers, 2019 to 2024). Acute myeloid leukemia (AML) is a group of neoplasms arising from precursor cells committed to the myeloid cell-line differentiation. "For instance, glycolysis was boosted by STAT5 (signal transducer and activator of transcription 5A) in acute myeloid leukemia (AML) cells to provide excessive lactide for lactylation of PD-1, making tumor cells susceptible to immune checkpoint inhibitors (ICIs)." (PMID 39257588, 2024).
cervical cancer (4 papers, 2016 to 2022). A primary or metastatic malignant neoplasm involving the cervix. "This type of cancer has been reported to express a variety of molecules, some of which are associated with the progression of HPV-associated cervical cancer, such as STAT5A, hypoxia-inducible factor 1α (HIF-1α), and glucose transport protein 1 (GLUT1)." (PMID 27293315, 2016). "In breast or cervical cancer, excessive STAT5A activation triggered by hyper-phosphorylation or self-mutation is a key mechanism for malignant tumor cell proliferation." (PMID 35517418, 2022). "In contrast, the expression of STAT5A was reduced around 70% in all HPV+ cervical cancer cells, consistent with previous work." (PMID 31817106, 2019). "Co-IP assays with an anti-STAT5A antibody demonstrated that endogenous STAT5A interacted with multiple PDC subunits, including PDHA1, PHDB, DLD, and DLAT in 293T, HeLa (a human cervical cancer cell line), MIHA (a human hepatocyte), and primary mouse hepatocytes." (PMID 34148062, 2021).
Hyperglycemia (4 papers, 2017 to 2025). An increased concentration of glucose in the blood. "According to previous reports, hyperglycemic cultured cells and DKD rats showed increased STAT5A levels, while silencing STAT5A in-vitro reversed the impact of elevated hyperglycemia." (PMID 41318413, 2025). "MCAT and its network with PTPN1, STAT5A are regulated in umbilical cord blood affected by maternal intrauterine hyperglycemia." (PMID 29088862, 2017). "In conclusion, MCAT and its crosstalk with PTPN1, STAT5A are increased in the umbilical cord blood affected by maternal uterine hyperglycemia." (PMID 29088862, 2017).
invasive breast carcinoma (4 papers, 2012 to 2023). A carcinoma that infiltrates the breast parenchyma. "Based on the dataset from TCGA, for 817 patients with breast invasive carcinoma, the expression of Notch3 was positively associated with the levels of STAT5A (p = 0.001 and Spearman r = 0.1154)." (PMID 38124049, 2023). "Unexpectedly, the analyses revealed frequent and selective loss of nuclear as well as total Stat5a protein in invasive breast cancer and lymph node metastases, whereas expression of Stat5b remained unchanged." (PMID 23036105, 2012). "Tumor levels of Stat5a and Stat5b mRNA in a cohort of 936 patients with available outcome data were then interrogated to determine whether expression of Stat5a or Stat5b in primary invasive breast cancer was associated with clinical outcome." (PMID 23036105, 2012). "For example, STAT5a expression was predictive of increased overall survival and response to endocrine therapy in ER-positive human invasive breast cancer." (PMID 32633727, 2020). "Total Stat5a protein, as well as nuclear localization of Stat5a, is frequently lost in invasive breast cancer and lymph node metastases." (PMID 23036105, 2012). "The present study used quantitative in situ analysis to reveal for the first time a significant reduction in total cellular and nuclear Stat5a protein levels in invasive breast cancer and lymph node metastases compared with normal breast epithelia and DCIS." (PMID 23036105, 2012). "The reduced levels of nuclear-localized Stat5a protein in invasive breast cancer and lymph node metastases are consistent with our previous reports showing a loss of Nuc-pYStat5a/b." (PMID 23036105, 2012). "There results demonstrated that STAT5A/5B may associated with BRCA aggression and STAT5A/5B may help to detect invasive breast cancer patients." (PMID 36862902, 2023). "Notably, we also find the expression level of STAT5A to be positively related to Notch3 expression in patients with invasive breast carcinomas." (PMID 38124049, 2023). "Having a better understanding of STAT5a pathway in pre-invasive breast cancer could lead to the development of personalized therapies for high risk DCIS patients." (PMID 32633727, 2020). "Thus, STAT5A and STAT5B may help to detect invasive breast cancer patients." (PMID 36862902, 2023).
liver cancer (4 papers, 2019 to 2025). An epithelial or non-epithelial malignant neoplasm that arises from the liver. "We further verified the regulation of tumor cGAS by TET2 and STAT5A signaling in human liver cancer samples and found that high tumor TET2 and p-STAT5A expressions were associated with high tumor cGAS expression." (PMID 38177099, 2024). "Next, we investigated the protein expression levels of tumor TET2-p-STAT5A-cGAS-LRRC8C-endothelial STING axis in tumor biopsies from liver cancer patients." (PMID 38177099, 2024). "Together, these findings provide conclusive evidence for the crucial involvement of tumor Tet2 and Stat5a in VC-mediated vascular normalizing effects and the combinational efficiency of VC and anti-PD-L1 therapy in liver cancer." (PMID 38177099, 2024). "Since IL2RB and IL2RG are sufficient to form functional receptor for transmitting signals from IL-229, liver cancer cells could also respond to IL-2 secreted by T cells and led to STAT5A activation." (PMID 38177099, 2024). "Together, these results indicate that IL-2-activated STAT5A recruits TET2 binding to the cGAS locus to promote cGAS demethylation and transcription, leading to cGAS upregulation in liver cancer." (PMID 38177099, 2024). "The present work identifies TET2 methylcytosine dioxygenase as a responsible enzyme for cGAS demethylation and reveal that activated STAT5A recruits TET2 binding to the cGAS locus to promote cGAS demethylation and transcription, resulting in cGAS upregulation in liver cancer cells." (PMID 38177099, 2024). "Collectively, these data show that tumor TET2-p-STAT5A-cGAS-LRRC8C-endothelial STING axis is linked to vascular normalization and immune infiltration in human liver cancer." (PMID 38177099, 2024). "In vitro, disruption of Stat5a, but not Stat1, which exhibited a positive correlation with cGAS regardless of TET2 expression, impaired Cgas expression in liver cancer cells." (PMID 38177099, 2024).
melanoma (4 papers, 2021 to 2024). A malignant, usually aggressive tumor composed of atypical, neoplastic melanocytes. "In melanoma, high STAT5a expression was significantly associated with favorable overall survival (lnHR = −1.788 [−2.975, −0.6004], P-value = 0.00317)." (PMID 37369132, 2023). "Then we search for the STAT5A/B mutations of melanoma patients in cBioPortal, which could visualize the databases of published researches." (PMID 34051805, 2021). "YTHDF2 was identified to promote multiple melanoma cell proliferation via STAT5A/MAP2K2/p-ERK axis." (PMID 37256443, 2024). "And the melanoma cell line A375 has no mutation of STAT5A/B tested by WES." (PMID 34051805, 2021). "Among the 5 STAT5A/B mutant melanoma samples, there has no significant increase in PD-L1 mRNA than STAT5A/B wildtype samples." (PMID 34051805, 2021).
asthma (3 papers, 2011 to 2023). "The genome wide association studies (GWAS) have found that severe asthma is associated with the 17q21 chromosomal region; the region where codes some proteins like STAT5a." (PMID 28638418, 2017). "The association between asthma and the STAT5b isoform has been the most well studied relationship to date but a potential role for the STAT5a isoform is unclear." (PMID 28638418, 2017). "However, the STAT5a down regulation in asthmatics and especially SRA is a notable finding which denotes on association between STAT5a and different level of asthma." (PMID 28638418, 2017). "Compared with the control group, the expression of Fos, Myl9 and Tlr4 in the asthma model was increased, while the expression of Smg7, Sumo2 and Stat5a was decreased." (PMID 36726128, 2023). "STAT5 consists of two isoforms, STAT5a and STAT5b, which can regulate lymphocyte proliferation, apoptosis, asthma and cancer." (PMID 36726128, 2023). "It has also been shown that STAT5a/b are important for lymphocyte proliferation, apoptosis, and have been used for targeted gene therapy and therapeutics (e.g., for asthma and cancer)." (PMID 28638418, 2017). "Meanwhile, down regulation of STAT5a in asthma, and especially SRA, is a notable finding which worth to be considered more in future studies." (PMID 28638418, 2017). "Fold change analysis (2−ΔΔCt) revealed the highest STAT5a transcript levels were in healthy controls, followed by the mild asthma and then SRA groups (the control group was set to 1.0)." (PMID 28638418, 2017). "In comparison to healthy controls, the levels of STAT5a were notably lower in patients with mild asthma and significantly least in those with SRA." (PMID 28638418, 2017). "This demonstrates that there is STAT5a down regulation in asthma and SRA cases, suggesting that this isoform has a role in the pathogenesis of asthma, particularly its severe form." (PMID 28638418, 2017). "Our results showed that STAT5a was decreased in the asthma model of mice, and this is supported by the another published research that the expression of STAT3 and STAT5a genes in the peripheral blood mononuclear lymphocytes were down-regulated in the severe refractory asthma." (PMID 36726128, 2023). "Additionally, based on the previously published literatures on asthma and inflammation, we screened out down-regulated genes, such as Smg7, Sumo2, and Stat5a, and up-regulated genes, such as Myl9, Fos and Tlr4." (PMID 36726128, 2023). "The STAT5a expression in healthy controls was nearly twice of patients with asthma." (PMID 28638418, 2017). "Although the exact mechanisms of asthma pathogenesis remain unclear, some studies have suggested possible mechanisms for how STAT5a may be involved." (PMID 28638418, 2017). "Using quantitative real-time polymerase chain reactions (qRT-PCR), the transcript levels of STAT3 and STAT5a were evaluated in peripheral blood mononuclear lymphocytes (PBML) isolated from 13 patients with SRA, 14 with mild asthma, and 30 healthy volunteers." (PMID 28638418, 2017).